P2RX4 (purinergic receptor P2X 4)
Description:
ATP-gated nonselective transmembrane cation channel permeable to potassium, sodium and calcium. CTP, but not GTP or UTP, functions as a weak affinity agonist for P2RX4 (By similarity). Activated by extracellularly released ATP, it plays multiple role in immunity and central nervous system physiology. Plays a key role in initial steps of T-cell activation and Ca(2+) microdomain formation (By similarity). Also participates in basal T-cell activity without TCR/CD3 stimulation (By similarity). Promotes the differentiation and activation of Th17 cells via expression of retinoic acid-related orphan receptor C/RORC. Upon activation, drives microglia motility via the PI3K/Akt pathway (By similarity). Could also function as an ATP-gated cation channel of lysosomal membranes (By similarity).
Synonyms: P2X4; P2X4R
Tractability: Small molecule: a structure with a bound ligand is known; a high-quality ligand is known; it belongs to a druggable protein family. Antibody: UniProt places it where antibodies can reach, with high confidence; its Gene Ontology location is reachable by antibodies, with high confidence; UniProt predicts a signal peptide or a membrane-spanning region. PROTAC: its protein half-life has been measured; a small molecule that binds it is known.
Target class: Ligand-gated ion channel; P2X receptor; Ion channel
Chemical probes: BAY-1797 (high quality), TNP-ATP
Safety:
Unwanted effects reported when the protein is acted on. In parentheses: how it was acted on, where the effect was seen, and who reports it.
decreased convulsions (inhibition, acute dosing; nervous system, renal, immune; source: Lynch et al. (2017))
decreased inflammation (inhibition, acute dosing; nervous system, renal, immune; source: Lynch et al. (2017))
decreased pain (inhibition, acute dosing; nervous system, renal, immune; source: Lynch et al. (2017))
hemolysis (activation, acute dosing; nervous system, renal, immune; source: Lynch et al. (2017))
increased pain (activation, acute dosing; nervous system, renal, immune; source: Lynch et al. (2017))
increased urinary sodium excretion (activation, acute dosing; nervous system, renal, immune; source: Lynch et al. (2017))
increased urine excretion (activation, acute dosing; nervous system, renal, immune; source: Lynch et al. (2017))
neurodegeneration (activation, chronic dosing; nervous system, renal, immune; source: Lynch et al. (2017))
Gene: Protein-coding gene on chromosome 12 (121,210,065 to 121,234,112, forward strand). Ensembl gene ENSG00000135124.
Subcellular location: Cell membrane; Lysosome membrane
Pathways (Reactome):
Hemostasis: Elevation of cytosolic Ca2+ levels; Platelet homeostasis
Disease: Purinergic signaling in leishmaniasis infection
Gene Ontology:
Molecular function: cadherin binding; extracellularly ATP-gated monoatomic cation channel activity; identical protein binding; ligand-gated calcium channel activity; protein binding; purinergic nucleotide receptor activity; ATP binding; copper ion binding; signaling receptor binding; zinc ion binding; monoatomic ion channel activity
Biological process: apoptotic signaling pathway; calcium ion transmembrane transport; cellular response to ATP; membrane depolarization; monoatomic ion transmembrane transport; negative regulation of cardiac muscle hypertrophy; positive regulation of blood vessel endothelial cell migration; positive regulation of calcium ion transport into cytosol; positive regulation of calcium-mediated signaling; positive regulation of endothelial cell chemotaxis; purinergic nucleotide receptor signaling pathway; regulation of blood pressure; regulation of cardiac muscle contraction; relaxation of cardiac muscle; response to ATP; response to fluid shear stress; signal transduction; behavioral response to pain; calcium-mediated signaling; cellular response to zinc ion; endothelial cell activation; positive regulation of calcium ion transport; positive regulation of microglial cell migration; positive regulation of nitric oxide biosynthetic process; positive regulation of phosphatidylinositol 3-kinase/protein kinase B signal transduction; and 16 more
Cellular component: cell junction; extracellular exosome; lysosomal membrane; membrane; perinuclear region of cytoplasm; plasma membrane; cell body; postsynapse
Genetic constraint (gnomAD): Loss-of-function variants: 38 observed, 46.11 expected, observed/expected ratio (o/e) 0.82, 90% interval 0.63 to 1.08. The upper end of that interval is the gene's LOEUF score, 1.08, which puts it in group 4 of 6, group 1 being the genes least tolerant of losing a copy. Missense variants: 469 observed, 492.3 expected, observed/expected ratio (o/e) 0.95, 90% interval 0.88 to 1.03. Synonymous variants: 190 observed, 185.57 expected, observed/expected ratio (o/e) 1.02, 90% interval 0.91 to 1.15.
Homologues: Orthologues: dog P2RX4 (89% identical), pig P2RX4 (88% identical), chimpanzee P2RX4 (87% identical), mouse P2rx4 (87% identical), rabbit P2RX4 (87% identical), rat P2rx4 (86% identical), guinea pig P2RX4 (78% identical), macaque P2RX4 (76% identical), tropical clawed frog p2rx4 (68% identical), zebrafish p2rx4a (57% identical). Paralogues in human: P2RX1 (49% identical), P2RX5 (48% identical), P2RX2 (46% identical), P2RX7 (45% identical), P2RX3 (44% identical), P2RX6 (43% identical).
Diseases named in the same sentence as P2RX4 in open-access papers:
P2RX4 is named in the same sentence as 162 diseases in open-access papers, as found by Europe PMC text mining. Sharing a sentence is not in itself a finding about the gene and the disease. The quoted sentences say what the papers report.
Stroke (16 papers, 2012 to 2025). Sudden impairment of blood flow to a part of the brain due to occlusion or rupture of an artery to the brain. "Interestingly, when specifically deleting P2rx4 in myeloid cells using LysM-Cre mice, only female mice showed a reduction in infarct size, suggesting a sex difference in the P2X4 response after stroke." (PMID 36917241, 2023).
breast carcinoma (11 papers, 2011 to 2025). "Similar to breast cancer, P2RX4 is expressed significantly higher in PCa patient tissues and cell lines (PC3, LNCap, C4-2B4) compared to benign and healthy tissues." (PMID 41009609, 2025). "Targeting autophagic abilities in breast cancer to stem their aggressiveness has been suggested by previous studies, and P2RX4 could be a good target for impairing autophagy for breast cancer therapy." (PMID 41009609, 2025). "P2RX4 signaling also affects autophagy, which could increase the aggressiveness of breast cancer cells." (PMID 41009609, 2025). "In breast cancer, CTSD and P2RX4 expression are correlated, where tumor and metastatic cells have much higher levels of CTSD in the ECM and P2RX4 expression compared to healthy neighboring cells." (PMID 41009609, 2025). "In breast cancer, EMT and autophagy are promoted by P2RX4 as observed by changes in the transcriptional expression of mesenchymal markers and autophagy markers p62 when P2RX4 is silenced." (PMID 41009609, 2025).
neuropathic pain (11 papers, 2016 to 2024). Chronic pain caused by damage to nerve fibers. "Within models of neuropathic pain, it has been suggested that activation of P2rx4 induced microglia to release brain-derived neurotropic factors (BDNF), which then affected neuronal activity by modulating GABAergic activity." (PMID 29925434, 2018).
prostate carcinoma (11 papers, 2011 to 2025). A carcinoma that arises from epithelial cells of the prostate gland. "P2RX4, a member of this family, has been implicated in breast and prostate cancers and shown to promote tumor progression and aggressiveness." (PMID 41009609, 2025). "While there is a paucity of data on the effect of this genetic variant on P2RX4 function, this candidate genetic marker in prostate cancer development warrants further independent replication or functional validation of this genetic variant." (PMID 34253731, 2021). "Many unanswered questions remain about the role of P2RX4 in prostate tumorigenesis at the molecular level, warranting the functional characterisation of P2RX4 polymorphisms in prostate cancer with potential translational relevance." (PMID 34253731, 2021). "The P2RX4 rs25644 allele GG was associated with a high risk of prostate cancer, whereas it was associated with a low risk of cancer recurrence in patients with prostate cancer." (PMID 34253731, 2021). "Immunotherapeutic strategies hold potential for the treatment of breast and prostate cancers that overexpress P2RX4, and further research is needed to optimize their efficacy and minimize side effects." (PMID 41009609, 2025). "In prostate cancer, P2RX4 is involved in enhancing tumor formation, mobility, TGFβ-1 induced invasiveness, and epithelial-to-mesenchymal transition." (PMID 36333684, 2022). "These genetic findings highlight, for the first time, the involvement of P2RX4 endolysosomal ion channels in various aspects of cancer phenotypes other than prostate cancer growth, cancer pain, and tumour microenvironment." (PMID 34253731, 2021). "This explains our finding that a genetic variant is significantly correlated with an increased risk of prostate cancer and provides insights into the role that P2RX4 plays in prostate cancer pathology." (PMID 34253731, 2021). "Because of the worldwide prevalence of breast and prostate cancers and their increasing occurrence in the Asian population, we review here the role of P2RX4 and its signaling pathways that could be involved in cell physiological and oncogenic processes." (PMID 41009609, 2025). "The purinergic receptor P2RX4 contributes to the malignant behavior of breast and prostate cancers." (PMID 41009609, 2025). "P2RX4 mediates tumor growth and invasiveness in prostate cancer." (PMID 41009609, 2025). "And P2RX4 supports tumor growth and metastasis in other types of cancer like prostate cancer." (PMID 38157255, 2023).
Hypertension (9 papers, 2013 to 2025). The presence of chronic increased pressure in the systemic arterial system. "The annotation of DEGs in RGD (Rat Genome Database) revealed 18 genes associated with hypertension, and according to DAVID, four additional DEGs (Acta2, Hba2, P2rx4, and Sult1a1) were defined as related to regulation of BP." (PMID 32039698, 2019). "Altogether, we found nine genes (Cst3, Cyp11b2, Ephx2, Fn1, Igfbp2, P2rx4, Prkcd, RT1-Ba, and Sult1a1) annotated in the RGD as associated with hypertension in this group." (PMID 26822062, 2016). "Based on this, we suggest that down-regulation of the P2rx4 gene in the ISIAH hypothalamus might contribute to hypertension development." (PMID 26822062, 2016).
multiple sclerosis (9 papers, 2018 to 2025). A progressive autoimmune disorder affecting the central nervous system resulting in demyelination. "However, in EAE (an animal model of multiple sclerosis, which is another chronic inflammatory disease of the brain and spinal cord), the blockade of P2RX4 signaling exacerbates clinical signs, favors microglial activation to a pro-inflammatory phenotype, and inhibits myelin phagocytosis." (PMID 35610277, 2022). "Altogether, studies from this section suggest that subjects carrying genetic variants of the P2RX4 gene may have higher risks for developing HIV-associated sensory neuropathy, blood pressure complications, osteoporosis, multiple sclerosis, and impaired immune responses." (PMID 33897694, 2021).
depression (7 papers, 2017 to 2026). "However, there is scarce evidence about the alterations in P2RX7 or P2RX4 levels and in behavioral consequences induced by previous exposure to stress, a major risk factor for depression in humans." (PMID 31656696, 2019). "Excessive/sustained release of ATP during stress exposure could trigger the activation of P2RX7 and/or P2RX4 in brain regions important for stress and depression." (PMID 31656696, 2019).
epilepsy (7 papers, 2013 to 2021). A brain disorder characterized by episodes of abnormally increased neuronal discharge resulting in transient episodes of sensory or motor neurological dysfunction, or psychic dysfunction. "Lastly, while several purinergic receptors have been shown to modulate microglial function during epilepsy, including P2ry12 and P2rx7, we only observed significantly increased expression of P2rx4." (PMID 29925434, 2018). "In pathological conditions, such as neuropathic pain or epilepsy, P2RX4 expression is up-regulated in both hippocampal and spinal neurons and microglia." (PMID 29343707, 2018).
neuropathy (7 papers, 2017 to 2023). A disorder affecting the nervous system that manifests with pain, tingling, numbness, and/or muscle weakness. "To decipher which cell type contributes to tactile allodynia observed during neuropathy, we specifically deleted p2rx4 in myeloid cells using tamoxifen-inducible Cx3cr1CreERT2:P2X4flox/flox mice, in which P2X4 is specifically deleted in myeloid cells." (PMID 37860691, 2023).
asthma (6 papers, 2016 to 2024). "Taken together, these data suggest that of the P2X receptors, P2RX1, P2RX4, and P2RX7 are likely to be the most credible targets for respiratory diseases such as asthma." (PMID 35386996, 2021). "Notably, P2RX1, P2RX4, P2RX7, P2RY1, P2RY11, and P2RY14 were revealed as the most highly expressed purinergic receptors in lung tissue, therefore suggesting that these receptors have good potential as therapeutic targets for asthma and other respiratory diseases." (PMID 35386996, 2021).
heart failure (6 papers, 2012 to 2023). Inability of the heart to pump blood at an adequate rate to meet tissue metabolic requirements. "Myh-7 and Nppa are wildly used as markers for cardiac hypertrophy and pressure overload, while P2RX4 is considered to play a beneficial role in alleviating cardiac hypertrophy and heart failure in a canine calsequestrin (CSQ) transgenic mouse model." (PMID 34579143, 2021).
liver fibrosis (5 papers, 2021 to 2022). "Furthermore, fibroblast P2rx4 was upregulated in lung fibrosis and has previously been found both to have a pro-fibrotic role and to be necessary for fibroblast calcium in liver fibrosis." (PMID 35634278, 2022).
Obesity (5 papers, 2020 to 2025). Accumulation of substantial excess body fat. "The two genes (P2RX4 and RADIL), identified in the IoW and further confirmed in the ALSPAC, had some limited evidence of connections with BMI or obesity." (PMID 33766110, 2021).
hepatocellular carcinoma (4 papers, 2021 to 2022). A malignant tumor that arises from hepatocytes. "In hepatocellular carcinoma, P2RX4 is highly expressed and positively related to the growth and proliferation of cancer cells." (PMID 36333684, 2022).
lung fibrosis (4 papers, 2022 to 2025). "We found that fibroblast-specific deletion of the eATP receptor P2rx4 decreased lung fibrosis in mice." (PMID 40875483, 2025). "Despite these limitations, our results reveal a novel role for macrophages in paracrine regulation of fibroblast calcium, as well as a specific dependency on Cx43, and raise the profile of P2rx4 as a potential therapeutic target for lung fibrosis." (PMID 35634278, 2022). "Fibroblast-specific deletion of P2rx4 in mice decreased lung fibrosis and collagen expression in lung fibroblasts in the bleomycin model." (PMID 35634278, 2022). "Taken together, these studies reveal a Cx43-dependent profibrotic effect of lung macrophages and support development of fibroblast P2rx4 as a therapeutic target for lung fibrosis." (PMID 35634278, 2022). "Nonetheless, in both species, we confirmed a P2RX4/IL-6/ARG1, myeloid-mesenchymal circuit that is functionally important in lung fibrosis." (PMID 40875483, 2025).
allergic asthma (3 papers, 2016 to 2023). A asthma with a basis in a pathological type I hypersensitivity reaction. "In conclusion our data suggests that P2RX4-signaling contributes to AAI pathogenesis by regulating DC mediated Th2 cell priming via modulating IL-1ß secretion and selective P2RX4-antagonists might be a new therapeutic option for allergic asthma." (PMID 27863396, 2016). "Although P2RX7 has already been implicated in allergic asthma, the role of P2RX4 in airway inflammation has not been elucidated yet." (PMID 27863396, 2016).
age-related macular degeneration (2 papers, 2021 to 2024). Age-related loss of vision in the central portion of the retina (macula), secondary to retinal degeneration. "The loss-of-function polymorphism (Tyr315Cys) in the P2RX4 gene was associated with increased susceptibility to age-related macular degeneration (AMD) in a study of 744 patients and 557 age-matched Caucasians." (PMID 33897694, 2021).
cardiac hypertrophy (2 papers, 2021). "Next generation sequence (NGS) analysis indicated a modulation of the expression levels of several cardiac hypertrophy-associated genes, including GPR22, Myh7, Nppa, P2RX4, and Npy by MFE." (PMID 34579143, 2021). "Furthermore, to validate the expression of hypertrophy-related gene expression in ARVs treated cardiomyocytes, we selected Hopx, Ackr3, and P2rx4 genes, based on their significance and the relatedness to their role in cardiac hypertrophy." (PMID 34943964, 2021).
cervical cancer (2 papers, 2018 to 2024). A primary or metastatic malignant neoplasm involving the cervix. "P2RX4 (also known as P2X4) is a member of the purinergic receptors, which were reported to be associated with different cancer types including colorectal, esophageal, prostate, and cervical cancer." (PMID 30020984, 2018). "Calcin, in particular, induces an elevation in intracellular calcium levels through a P2RX4-dependent mechanism, thereby mediating apoptosis in breast and cervical cancer cell lines." (PMID 39555060, 2024).
eosinophilia (2 papers, 2016 to 2020). "Both, P2RX4 antagonist 5-BDBD treatment and P2rx4 deficiency resulted in an alleviated broncho alveolar lavage fluid eosinophilia, peribronchial inflammation, Th2 cytokine production and bronchial hyperresponsiveness." (PMID 27863396, 2016).
mood disorder (2 papers, 2024 to 2025). A cognitive disorder a disturbance in which the person's mood is hypothesized to be the main underlying feature. "Our study’s identification of elevated P2RX4 expression is a key finding, as this receptor has not been extensively studied in MDD or mood disorders." (PMID 40076453, 2025).
prostate adenocarcinoma (2 papers, 2021 to 2025). "However, it is well documented that PC3 cells do not secret IL-2 and our gene correlation analysis using GEPIA also confirms that there is no gene expression correlation between P2RX4 and IL-2 in prostate adenocarcinoma but a positive correlation in whole blood." (PMID 40515881, 2025).
Sensory neuropathy (2 papers, 2021 to 2023). Peripheral neuropathy affecting the sensory nerves. "Analysis of SNP polymorphisms in the P2RX4 gene suggested an association of this gene with susceptibility to HIV-associated sensory neuropathy, even though there was a stronger association of the disease with the P2X4 contiguous gene, CAMKK2." (PMID 33897694, 2021).
acute leukemia (1 paper, 2025). A clonal (malignant) hematopoietic disorder with an acute onset, affecting the bone marrow and the peripheral blood. "Finally, P2RX4 (cg19357999) is upregulated in relapsed acute leukemia, promoting plasma cell survival through purinergic signaling." (PMID 40730747, 2025).
breast tumour (1 paper, 2023). "It has also been demonstrated that P2RX4 enhances BC invasiveness, breast tumour growth, and metastasis." (PMID 38259456, 2023).